MIR604 (microRNA 604)
Synonyms: hsa-mir-604; MIRN604
Gene: MicroRNA gene on chromosome 10 (29,545,004 to 29,545,097, reverse strand). Ensembl gene ENSG00000207612.
Gene Ontology:
Biological process: miRNA-mediated post-transcriptional gene silencing
Cellular component: RISC complex
Diseases named in the same sentence as MIR604 in open-access papers:
MIR604 is named in the same sentence as 2 diseases in open-access papers, as found by Europe PMC text mining. Sharing a sentence is not in itself a finding about the gene and the disease. The quoted sentences say what the papers report.
cancer (1 paper, 2021). A tumor composed of atypical neoplastic, often pleomorphic cells that invade other tissues. "Additional results from the METABRIC datasets showed that ORN could characterize critical mechanisms of cancer and connect them to less studied somatic mutations (e.g., BAP1, MIR604, MICAL3, and telomere activities), which may generate novel hypothesis for targeted therapy." (PMID 33819263, 2021).
MIR604 also shares sentences with these, for which no sentence is quoted: breast carcinoma (1 paper).